AR (androgen receptor)
Diseases named in the same sentence as AR in open-access papers (continued):
Sharing a sentence is not in itself a finding about the gene and the disease.
prostate carcinoma (continued). "Although it appears that the AR may have a far broader role in regulating CSCs than initially imagined, clearly, further studies are required to evaluate AR regulation of CSC phenotype in other cancers outside of prostate cancer." (PMID 26880966, 2016). "While these alterations seem to be independent of copy number alterations in the PDE4D locus and driven by AR and ERG binding, we also observed increased DNA methylation in the promoter region of PDE4D5, indicating a long lasting alteration of the isoform composition in prostate cancer tissues." (PMID 27683107, 2016). "Importantly, TQ, but not AT, was found to reduce both AR mRNA and AR protein levels in prostate cancer cells with a concomitant reduction in androgenic pathways." (PMID 26986969, 2016). "Prostate cancer (PCa) is no exception: well-differentiated, low-grade tumors (i.e., Gleason 6-7) contain glandular structures with tumor cells expressing differentiation markers such as androgen receptor (AR) and prostate-specific antigen (PSA)." (PMID 26871947, 2016). "In contrast, androgens do not induce ZEB1 in an AR-positive prostate cancer cell line." (PMID 26797644, 2016). "Of note is the reported finding that the serine protease kallikrein 4 (KLK4), which promotes prostate cancer growth, activated both the AR and mTORC1 axis due to negative interplay of KLK4 with the transcription factor PLZF (promyelocytic leukemia zinc finger)." (PMID 27557496, 2016). "It is noteworthy that AT did not inhibit either AR expression or activity in prostate cancer cells." (PMID 26986969, 2016). "Conversely, all hormone-naive prostate cancer specimens were AR-GSR negative." (PMID 27897170, 2016). "To understand the context of this new class of AR gene alteration, we performed AR DNA-seq with six additional CRPC specimens obtained from transurethral resection of the prostate (TURP) procedures and 21 hormone-naive prostate cancer specimens obtained from prostatectomies." (PMID 27897170, 2016). "Castrate-resistant prostate cancer cells that acquire a completely AR-independent phenotype, whether of neuroendocrine or non-neuroendocrine type, typically display a more aggressive phenotype with rapid disease progression." (PMID 27276714, 2016). "Demonstrating that this co-regulatory mechanism is relevant in a prostate cancer setting required a prostate cancer cell line with stable knockdown of FKBP52 protein in which to assess β-catenin effects on AR activity in the presence or absence of significant levels of FKBP52." (PMID 26207810, 2015). "A recent paper reported the loss of B55gamma promotes androgen ligand depletion-resistant prostate cancer growth, which was independent of AR-mediated transcriptional programs indicating B55gamma might be a tumor suppressor gene." (PMID 25792973, 2015). "Whether prostate cancer stem cells have the features of EMT and roles of AR in this process was unclear, in this study, we would investigate EMT characteristics in prostate cancer S/P cells, and the roles of AR in regulating EMT and characteristics of S/P cells." (PMID 25943311, 2015). "AR/miR-190a/YB-1 signaling forms an auto-regulatory negative feedback loop in prostate cancer, where androgen/AR inhibits miR-190a expression through direct binding to the ARE in the miR-190a promoter, and miR-190a inhibits AR expression and activity through binding 3′-UTR of YB-1 gene." (PMID 26314494, 2015). "In contrast, CPT1 expression has been reported to be higher in the low metastatic potential, androgen receptor negative LNCaP prostate cancer cell line compared to the high metastatic potential, androgen receptor positive PC3 and DU145 prostate cancer cell lines." (PMID 25866768, 2015). "However, the role of these phosphorylation sites in general AR function in prostate cancer cells that have not been transfected with activated Ack1 has not been well characterized." (PMID 25950519, 2015).
prostate carcinoma (continued). "AIZ-AR cell line is derived from human prostate carcinoma epithelial cell line 22Rv1 expressing endogenous AR (no extra AR vector co-transfected) that was transfected with reporter plasmid containing sequence of androgen response element from promoter of human prostate-specific antigen (PSA)." (PMID 25811655, 2015). "This may play a crucial role in the development of hormone independence in a subset of prostate cancers that do not express AR." (PMID 25690296, 2015). "Therefore, AR-independent and RUNX1-regulated signals, which remain to be clarified, may be important for prostate cancer progression." (PMID 25537508, 2015). "Activation of PI3K signalling as a result of treatments targeting the AR may therefore enable prostate cancer cells to survive and proliferate without androgens." (PMID 26501081, 2015). "Interestingly, PAC usually contains a small population (usually ~1%) of scattered neuroendocrine-like prostate cancer (NEPC) cells that do not express AR and PSA." (PMID 25797256, 2015). "It is well-established that CRPC cells remain addicted to AR signaling; therefore, the inhibitory effect on AR, rather than the antimitotic activity, could possibly be the predominant mechanism of action for taxanes in prostate cancer." (PMID 26160840, 2015). "Interestingly, inhibition of 5-Lox was found to kill both androgen-receptor positive as well as androgen-receptor negative prostate cancer cells." (PMID 25875826, 2015). "The AR negative tumor PC_6864 carried a KRAS p.G12R mutation that is known to cause constitutive KRAS activation in cancers of the colon, pancreas and lungs, but is less common in prostate cancer." (PMID 25749039, 2015). "A panel of five prostate cancer cell lines, VCaP, DU-145, PC-3, LNCaP and 22RV1, characterized by different expression levels of the androgen receptor (AR) and T2E gene fusion, and non-malignant RWPE-1 prostate cells was analyzed for the expression of different components of the IGF system." (PMID 25906745, 2015). "It is observed that in hormone refractory or androgen-independent (AI) prostate cancer cells, a large pool of androgen receptor is translocated into the nucleus even in the absence of androgen and thus leads to the transcriptional activation of target genes resulting in tumor growth." (PMID 25973397, 2015). "Furthermore, PABPC1 knockdown inhibited proliferation of all the tested AR-positive but not the AR-negative PC3 prostate cancer cells." (PMID 26176602, 2015). "Next, we analyzed the role of RUNX1 in AR-negative prostate cancer cells." (PMID 25537508, 2015). "Additionally, knockdown of PABPC1 inhibited transactivation of the PSA promoter by NAR (AR lacking the LBD) and attenuated proliferation of AR-positive prostate cancer cells." (PMID 26176602, 2015). "A recent paper claimed that B55gamma might be a tumor suppressor gene in prostate cancers, they reported the loss of B55gamma promotes androgen ligand depletion-resistant prostate cancer growth, which was independent of AR-mediated transcriptional programs." (PMID 25792973, 2015). "An important question that arises from our study is the mechanism by which LMTK2 might be regulating AR transcription and cell proliferation in the absence of exogenous androgen in prostate cancer cells." (PMID 26008968, 2015). "To determine the direct but androgen-independent effects of hypercholesterolemia on advanced prostate cancer progression, we used an androgen-receptor negative prostate cancer cell line PC-3, expressing the luciferase gene in an orthotopic xenograft mouse model." (PMID 25924234, 2015). "Furthermore, the mechanism underlying the differential cytotoxic effect of plant-derived SAC-Par-4 on AR positive and AR negative human prostate cancer cells needs further investigation." (PMID 26500666, 2015). "However, the possibility that inhibition of the AR pathway engenders prostate cancer cells that are reliant on Wnt/β-catenin signaling has not been tested experimentally." (PMID 26509262, 2015).
prostate carcinoma (continued). "As described herein, we identified an AR-dependent non-nuclear signaling pathway, independent of integrin α6β1 transcription, leading to Src activation and subsequent cleavage and shedding of Matriptase, required for prostate cancer invasion." (PMID 25730905, 2015). "However, true to its hormone-regulated non-malignant ancestor, prostate cancer cells remain dependent on a ligand-activated androgen receptor (AR) to facilitate mitogenic responses enabled by genomic aberration." (PMID 25896606, 2015). "Many aspects of AR-V7 functionality and AR gene regulation identified herein recapitulate findings in the prostate cancer context, which is not surprising given the known similarities between these two malignancies, particularly in terms of endocrine signaling." (PMID 26554309, 2015). "Since, the AR is active in CRPC and is able to transcribe AR-dependent genes either in the presence of low levels of androgens or absence of androgens, we determined if a decrease in LMTK2 is involved in activating AR in androgen deprived prostate cancer cells." (PMID 26008968, 2015). "However, its influence on prostate cancer cell growth is likely mediated through the AR because PABPC1 knockdown inhibited proliferation of AR-positive prostate cancer cells, but not AR-negative PC3 cells." (PMID 26176602, 2015). "The rationale for not applying endocrine therapies in the adjuvant management of prostate cancer after prostatectomy is provided by multiple clinical trials, which illustrated limited to no clinical benefit of blocking AR function on disease-free survival of the entire population." (PMID 26412853, 2015). "Activating AR pathway mainly inhibits CX43 expression in prostate cancer cell membrane, and CX43 expression of cell membrane in nonmalignant prostate cells is at low level, which just provide the answer that AR pathway poorly affects CX43 expression in nonmalignant prostate cells." (PMID 26491675, 2015). "Thus, we conclusively demonstrate that PCGEM1 and PRNCR1 are not prognostic lncRNAs in prostate cancer and we refute suggestions that these lncRNAs interact in AR signaling." (PMID 24727738, 2014). "Interestingly, comparison of hormone-sensitive prostate cancer cell models to their CRPC-derivative models often demonstrated higher basal G6PD levels in the CRPC models, perhaps reflecting the high basal levels of AR activity in these cells." (PMID 24861463, 2014). "However, the relationship between androgen receptor and DNA methylation and the expression of miR-375 in prostate cancer cells is not yet known and therefore the subject of the present study." (PMID 24173286, 2014). "Interestingly, AR regulates Nrdp1 levels transcriptionally in androgen-dependent but not in castration resistant prostate cancer." (PMID 25400118, 2014). "Despite the studies confirming AhR ligand regulation of AR signaling, AhR may possess intrinsic functions that regulate growth of prostate cancers independent of AR status that has not been fully studied." (PMID 24755659, 2014). "The role of AR in prostate cancer initiation is accentuated by the seminal discovery that the oncogenic ETS family transcription factors, such as ERG and ETV1, are translocated to the loci of androgen regulated genes including TMPRSS2 in approximately 50% of all human prostate cancers." (PMID 24508459, 2014). "After a preliminary stage of hormone-sensitive disease that is treated by androgen-deprivation therapy and agents directly inactivating the AR, patients progress to castrate resistant prostate cancer (CRPC) for which there is no curative treatment available with an extremely poor prognosis." (PMID 25216524, 2014). "Inhibiting prostate cancer nuclear export, independent of androgen receptor status, through agents that offer increased efficacy and reduced toxicity may benefit a bigger cohort of prostate cancer patients including castration resistant patients." (PMID 25026284, 2014).
prostate carcinoma (continued). "Metformin might mediate a similar effect in AR negative and positive prostate cancer cells in addition to its ability to downregulate AR." (PMID 24484909, 2014). "Indeed, an AR responsiveness persists in the androgen-dependent to -independent transition of prostate cancer and, with its co-activator SRCAP, AR could potentially bring the over-expressed H2A.Z.1 to different promoters." (PMID 24398858, 2014). "Metformin inhibited the migration of AR-positive as well as AR-negative prostate cancer cells." (PMID 24484909, 2014). "Following our previous research studies, our present data further define the key role of calpain 2 and not calpain 1 in prostate cancer progression, especially in cancer invasion and metastasis with its overexpression and enhanced activity in AR-negative prostate cancer cells." (PMID 24297527, 2014). "Interestingly, ERα is expressed in all prostate cancers, including those that lack AR expression, while it is absent in normal prostate epithelium." (PMID 25415230, 2014). "The oestrogen receptor alpha (ERα) is expressed in prostate cancers, independent of AR status." (PMID 25415230, 2014). "In prostate cancer (PCa) cells, ADT may enhance AR activity through induction of oxidative stress." (PMID 24466341, 2014). "Regardless of whether AR promotes or inhibits autophagy in prostate cancer, there is a consistent finding among these different studies that AR does play a role in cancer cell growth." (PMID 25140630, 2014). "Interestingly, also AR negative malignant prostate cancer cells (PC-3) exhibit an increased IGF-2 expression like LNCaP at higher AA concentration." (PMID 25332874, 2014). "Thus, we conclude that although the down-regulation of D-type cyclins leads to cell cycle arrest in the G0/G1 phase, it is not sufficient for promoting NED in AR-positive prostate cancer cells." (PMID 24884804, 2014). "Given the critical role of AR activation in prostate cancer initiation and progression, negative feedback regulation of MID1 by the AR may be an important and effective way in order to strictly control AR signaling." (PMID 24913494, 2014). "Similarly, we found that acoustophoretic processing neither affected the cell viability of prostate cancer cells nor altered their prostate-specific antigen secretion following androgen receptor activation." (PMID 23724038, 2013). "It has been known that half-life of AR protein is prolonged in the presence of agonistic steroids including testosterone, dihydrotestosterone, R1881 (synthetic androgen), and other nonandrogenic steroids in prostate cancer cells and others." (PMID 23896594, 2013). "However, it is not obvious from our study that PTEN and AR expression were inversely correlated in prostate cancer, as previously reported." (PMID 24098661, 2013). "While MEK-ERK activation is necessary and sufficient to mediate Raf-induced androgen receptor (AR) downregulation in prostate cancer cell lines irrespective of AR sensitivity, patients who have failed hormone ablation therapy display elevated ERK1/2 signal activation in recurrent tumors." (PMID 23620784, 2013). "Thus, pharmacological blockade of HSP90 can overcome signaling redundancies and mechanisms of drug resistance commonly observed in many cancers and simultaneously targets two major tumor maintenance pathways in prostate cancer cells, the PI3K-AKT-mTOR and AR pathways." (PMID 23863691, 2013). "We analyzed 110 primary prostate cancer samples, 70 metastatic tumor samples from 11 patients, and 27 xenograft tissues derived from 22 advanced prostate cancer patients using fluorescence in situ hybridization (FISH) analysis with probes targeting the TMPRSS2/ERG, PTEN, and AR gene loci." (PMID 24098661, 2013).
prostate carcinoma (continued). "Truncated AR species that composes only N-terminal domain (NTD) and DNA-binding domain (DBD) but lacks ligand-binding domain (LBD) and C-terminal domain (CTD) have been recently discovered as novel molecular mechanisms for the castration-resistant progression of prostate cancer." (PMID 23896594, 2013). "Fourth, despite the frequency of AR expression in primary breast cancers, the function and role of the receptor may not be the same as in prostate cancer." (PMID 24324894, 2013). "Finally, the dose of (±)-DR103 required to observe antiproliferative effects (10 μM) did not impact the growth of DU145 (an AR-null human prostate cancer cell line), supporting the specificity of the antiandrogen." (PMID 23580326, 2013). "However, Cdc37 knockdown inhibited growth of androgen receptor negative Prostate Carcinoma (PC-3 and DU-145) as effectively as it affected androgen-requiring LnCap cells." (PMID 24278769, 2013). "Importantly, androgen-independent prostate cancer cells showed a prolonged half-life of AR in the absence of androgen, indicating that AR stabilization has a potential role in AR overexpression in CRPC." (PMID 23896594, 2013). "We also overexpressed AR in the M12 prostate cancer cell line that does not normally express AR." (PMID 23704919, 2013). "However, critical downstream AR target genes of this type that account for AR dependent, ligand-independent prostate cancer cell survival have not been fully clarified." (PMID 23704919, 2013). "Loss of FOXA1 expression by targeted siRNA transfection in breast and prostate cancer cell lines results in reduction of growth suggesting an essential role in the proliferation of both cancers yet the mechanistic role for FOXA1 in ER and AR biology appears to be different." (PMID 23420418, 2013). "Interestingly, PathVisio analysis comparing androgen-dependent with androgen-independent prostate cancer did not detect the “Androgen Receptor Signaling Pathway” as significantly dysregulated." (PMID 23185449, 2012). "Pyrvinium pamoate was also found to act as a non-competitive androgen receptor (AR) inhibitor; PP inhibited endogenous AR activity in two prostate cancer cell lines, LANCaP and LAPC4, and reduced the expression of several androgen-responsive genes in LANCaP cells." (PMID 23061049, 2012). "Recently the male sex hormone androgen has been demonstrated to promote the recruitment of androgen receptor (AR) and topoisomerase II beta (TOP2B) to genomic breakpoints induced at androgen responsive genes including TMPRSS2: ERG fusion, the most common fusion detected in prostate cancer." (PMID 23272087, 2012). "Thus, the elevated signaling activity that occurs during progression to castration resistance can affect prostate cancer cell growth either through the AR or independent of the AR." (PMID 22761715, 2012). "Furthermore, we have shown that stress-induced CXCL8 signaling attenuates the sensitivity of prostate cancer cells to undergo apoptosis in response to DNA-damaging agents, Hsp90-directed inhibitors, death receptor agonists (TRAIL) and AR-targeted therapeutics such as bicalutimide (Casodex)." (PMID 22590561, 2012). "Although PSMC1 did not score in the PC3 cells in the initial shRNA library screen, siRNA knockdown of PSMC1 impaired viability of PC3 cells, raising the possibility that these antiproliferative effects may not be specific to AR-positive prostate cancer cells." (PMID 22509301, 2012). "Also, reciprocal feedback regulation between AR and PTEN in prostate cancer initiates a series of molecular events that contribute to growth survival and differentiation and may thus participate in ADT resistance." (PMID 22454635, 2012). "AR co-activators such as SRC-1, SRC-3, TIF-2 which could enhance the transcriptional activity of AR and contribute to the sensitization of AR to low levels of androgen concentrations are also elevated in prostate cancer." (PMID 22666381, 2012).